CHGA (chromogranin A)
Diseases named in the same sentence as CHGA in open-access papers (continued):
Sharing a sentence is not in itself a finding about the gene and the disease.
psoriasis (1 paper, 2023). An autoimmune condition characterized by red, well-delineated plaques with silvery scales that are usually on the extensor surfaces and scalp. "The analysed salivary immunoglobulin A, chromogranin A, and alpha-amylase are potential markers of the severity of psoriasis and the associated stress reaction." (PMID 37109650, 2023). "Immunoglobulin A, alpha-amylase and chromogranin A were selected as markers of stress and its impact on the course of psoriasis based on previous observations." (PMID 37109650, 2023).
psychological distress (1 paper, 2023). "Sample quality was not compared to other indicators such as salivary cortisol, amylase, or chromogranin A. The narrow range of K6 scores among participants may have contributed to the lack of correlation between salivary or plasma mBDNF and psychological distress." (PMID 37822121, 2023).
retinoblastoma (1 paper, 2016). A malignant tumor that originates in the nuclear layer of the retina. "Insulin growth factor 2 mRNA binding protein 1 (IGF2BP1), chromogranin A, fetuin A (ASHG), Rac GTPase-activating protein 1 and midkine that were found to be overexpressed in retinoblastoma were further confirmed by immunohistochemistry by staining 15 independent retinoblastoma tissue sections." (PMID 27799869, 2016).
Salmonella Infections (1 paper, 2022). Infections with bacteria of the genus SALMONELLA. "It was shown that Lgr5 and ChgA expressions were markedly decreased in the Salmonella infection group." (PMID 35163196, 2022).
sarcomatoid carcinoma (1 paper, 2013). A malignant epithelial neoplasm characterized by the presence of spindle cells and anaplastic morphologic features. "To include LCNEC, we expanded our antibody panel not only with vimentin, which can serve as a marker for sarcomatoid carcinoma, but also with neurendocrine markers (CD56, Synaptophysin, Chromogranin A)." (PMID 23418554, 2013).
scrapie (1 paper, 2020). A fatal disease of the nervous system in sheep and goats, characterized by pruritus, debility, and locomotor incoordination. "Similar to BAMBI, the staining of CHGA was stronger in scrapie brains, being significantly higher in Fc (p = 0.015), Cbl (p = 0.004) and Mo (p = 0.031)." (PMID 32370154, 2020). "Quantification of the density of the bands did not reveal significant changes in any of the analysed areas, although CHGA displayed a trend to upregulation in scrapie animals in Fc (p = 0.097)." (PMID 32370154, 2020). "Dysregulated genes (BAMBI and CHGA) were further analysed in a transgenic murine model (Tg338) of scrapie, and their protein distribution was determined using immunohistochemistry and Western blot." (PMID 32370154, 2020). "Protein CHGA in Tg338 mice presented an immunostaining pattern similar to that described for scrapie sheep." (PMID 32370154, 2020). "Whilst we found the CHGA (chromogranin A) protein mainly forming coarse intracytoplasmic aggregates within the neurons of natural scrapie and scrapie-infected transgenic mice, this protein locates at the ECM level in prion-resistant cell cultures." (PMID 32370154, 2020). "Finally, although both analysed proteins, BAMBI and CHGA, were overexpressed in the CNS of scrapie-infected animals, only BAMBI levels were significantly upregulated in the CSF of scrapie sheep at the clinical stage." (PMID 32370154, 2020). "The expression and distribution of proteins encoded by differentially expressed genes, i.e., BAMBI (BMP (bone morphogenetic protein) and activin membrane-bound inhibitor) and CHGA (chromogranin A), were subsequently evaluated in the CNS of scrapie-affected sheep and transgenic mice." (PMID 32370154, 2020). "BAMBI and CHGA distribution was not identical but the scores of these proteins were always higher in scrapie animals." (PMID 32370154, 2020). "Using natural ovine scrapie, our study certainly suggests that BAMBI and CHGA could play a relevant role in TSE neuropathology in vivo and may be involved in the characteristic neuroinflammatory response associated to these disorders." (PMID 32370154, 2020).
Senile plaques (1 paper, 2011). Senile plaques are extracellular deposits of amyloid in the gray matter of the brain. "Chromogranin A might synergistically enhance with beta-amyloid peptides the microglial neurotoxic effect and diminish microglial phagocytic activity in senile plaques." (PMID 22046305, 2011).
small cell neuroendocrine carcinoma of the prostate (1 paper, 2023). "One case was small cell neuroendocrine carcinoma of the prostate and was positive for chromogranin A (CGA), synaptophysin (SYN), and cluster of differentiation 56 (CD56)." (PMID 37576903, 2023).
stress-related disorder (1 paper, 2024). Stress-related disorders are mental health disorders that are a result of an atypical response to both short and long-term anxiety due to physical, mental, or emotional stress. "Relationships between stress-related disorders and serum and salivary biomarkers such as cortisol, dehydroepiandrosterone, chromogranin A, and proinflammatory cytokines were identified." (PMID 39531258, 2024).
thyroid follicular carcinomas (1 paper, 2024). "In assessing thyroid follicular carcinomas, Chromogranin-A (Cr-A) revealed multifocal and variable positivity in both cases, indicating a neuroendocrine component." (PMID 39591360, 2024).
Tricuspid regurgitation (1 paper, 2018). Failure of the tricuspid valve to close sufficiently upon contraction of the right ventricle, causing blood to regurgitate (flow backward) into the right atrium. "The diagnosis was confirmed by transthoracic echocardiography, which showed a severe tricuspid regurgitation with a patent foramen ovale, and by increased serum chromogranin A and urinary 5-hydroxyindoleacetic acid." (PMID 29386066, 2018).
ureteric obstruction (1 paper, 2025). "Imaging and biochemical tests revealed a primary ileocecal carcinoid tumour with hepatic metastases, RPF causing ureteric obstruction, and elevated chromogranin A/B and urinary 5-hydroxyindoleacetic acid (5-HIAA) levels." (PMID 40718235, 2025).
vitamin D deficiency (1 paper, 2022). A nutritional condition produced by a deficiency of VITAMIN D in the diet, insufficient production of vitamin D in the skin, inadequate absorption of vitamin D from the diet, or abnormal conversion of vitamin D to its bioactive metabolites. "This could implicate that vitamin D deficiency possibly downregulates chromogranin A secretion and consequently a lower level of catestatin." (PMID 35956112, 2022).
vulvar tumor (1 paper, 2022). "Immunohistochemical staining of the vulvar mass revealed that most of the vulvar tumor cells were positive for AE1/AE3, CAM5.2, neuron-specific enolase, CD56, and chromogranin A." (PMID 35351092, 2022).
xerostomia (1 paper, 2026). Dryness of the mouth resulting from reduced salivary secretion. "Furthermore, xerostomia was only related to chromogranin A concentration (p = 0.012)." (PMID 42118805, 2026).
tumor (517 papers, 1993 to 2026). "Immunohistochemically, the tumor showed strong and diffuse expression of all commonly used neuroendocrine markers, including chromogranin A, synaptophysin, syntaxin-1, and insulinoma-associated protein 1 (INSM1)." (PMID 40648806, 2025). "Chromogranin A (CgA) in serum is a commonly used biomarker for assessing tumor burden and monitoring treatment response, with elevated levels associated with tumor malignancy." (PMID 40535122, 2025). "Biomarkers in NETs (e.g., chromogranin A) typically have different diagnostic accuracy depending on the primary location of the tumor." (PMID 38893179, 2024). "Half of the patients with unresectable tumors survived longer than approximately 2 years with high age, high chromogranin A levels, and increased markers of tumor proliferation being linked to survival." (PMID 38201527, 2023). "Chromogranin A is an important tumor marker associated with it which is also useful in tumor volume determining as well as progression and disease response, and levels > 5000 μg/L indicate poor prognosis." (PMID 36960272, 2023). "We conclude that chromogranin-A protein associates with other cell organelles than secretory granules in this neoplasm." (PMID 34228212, 2022). "The results obtained from studying the Chromogranin A expression suggest that the secretion of biologically active substances by neuroendocrine cells causes an increase in tumor aggressiveness." (PMID 35163861, 2022). "Foci of neuroendocrine cells expressing chromogranin A were detected in patient L4 diagnostic TB (10%), in TB at progression (20%), and in 50% and 30% of tumor cells in the CDX and the cell line, respectively." (PMID 35511434, 2022). "In this process, the pathologist can analyze if the tumor cells express Chromogranin A and Synaptophysin, two proteins associated with the regulation of secretory vesicles." (PMID 34571751, 2021). "Chromogranin A is known to be elevated in 90% of gut NETs and it is associated with the tumor burden and presence of recurrence." (PMID 34567573, 2021). "NETest results and chromogranin A (CgA) levels were compared with clinical information including radiological imaging to evaluate the association with tumor characteristics." (PMID 30564197, 2018). "Plasmatic chromogranin A is a widely accepted tumor marker, used for diagnostic and prognostic purposes and to evaluate the response to treatment." (PMID 30007406, 2018). "Therefore, we foresee that the OC% metric can be combined with the existing prognosis predictors (e.g., SSTR avidity, tumor grade, Chromogranin A, multi‐gene molecular assays) to enhance risk stratification tools or prognostic models." (PMID 41499232, 2026). "Notably, markers of hepatic (Hep Par-1) and neuroendocrine (SYP, CHGA) differentiation were equally retained in the organoids, further underlining their ability to recapitulate the tumor biology in vitro." (PMID 35789568, 2022). "This may be due to improved diagnosis and the development of suitable, sensitive ways to measure this tumor, such as immunohistochemistry like chromogranin A (CgA) and diagnostic methods for tumor detection." (PMID 32563832, 2020). "Immunohistochemistry (IHC) should be conducted for all suspected cases of NETs with a minimal panel of markers (low-weight cytokeratin, synaptophysin and chromogranin A) to confirm the neuroendocrine nature of the tumour [IVA], and reduce the chance of diagnostic errors." (PMID 28194228, 2017). "Elevated levels of chromogranin A may also be caused by other neoplasias, diminishing its specificity." (PMID 28194228, 2017). "Here, Brachyury is more widely dispersed than ChgA, suggesting that Brachyury may have broader ranging functions in different regions of the tumour, possibly responding to regional tumour associated signals." (PMID 26862851, 2016). "Catestatin (CST), a Chromogranin A-derived peptide, exhibits potent anti-tumor activity by suppressing cancer progression across multiple stages." (PMID 42168158, 2026).
tumor (continued). "Established biomarkers such as Chromogranin A and the Ki-67 proliferation index remain vital for diagnosis and prognosis, while emerging markers, like circulating tumor DNA and microRNAs, show promise for enhancing disease monitoring and diagnostic accuracy." (PMID 40869136, 2025). "Chromogranin A and synaptophysin are markers of neuroendocrine differentiation, confirming the tumor’s neuroendocrine origin." (PMID 41467146, 2025). "Sellar tumor samples were consistently immunoreactive for neuroendocrine markers chromogranin A, synaptophysin, CD56/NCAM, and S100, further supporting a pituitary NET classification." (PMID 41203869, 2025). "These neoplasms are characterized by neuroendocrine marker expression, such as chromogranin A and synaptophysin, and are graded based on mitotic count and Ki-67 index." (PMID 40869648, 2025). "Histopathology confirmed a well-differentiated grade 2 tumor (Ki-67: 3%) positive for chromogranin A and CD56." (PMID 40869648, 2025). "Instead of isolated proteins, we identified a downregulated network of EEC markers (CHGA, GCG, PYY, NEUROD1) associated with tumor processes, reduced survival, and poor chemotherapy responses." (PMID 41303610, 2025). "Immunohistochemistry demonstrated that the tumor cells were positive for chromogranin A, synaptophysin, and CD56." (PMID 40091949, 2025). "In humans, neoplasms from C cells typically express calcitonin and neuroendocrine markers such as chromogranin A and INSM1, alongside variable expression of CK7." (PMID 41320889, 2025). "MTV and TLU correlated moderately but significantly with the tumor marker chromogranin A and with the biochemical secretion, supporting the utility of PET/CT as a diagnostic tool for PPGL." (PMID 40445313, 2025). "In the different studies that evaluated the IHC profile of these neoplasms, chromogranin A was the most frequently expressed marker with positivity rates above 50%." (PMID 41464736, 2025). "Immunohistochemical staining for chromogranin A (CgA) and synaptophysin was performed in all tumor tissue samples, and both markers were positive in all cases." (PMID 41427045, 2025). "The maximum anti-tumor effects occur in patients with hepatic tumor burden ≤10% or those undergoing primary resection, which are irrelevant to functional status, serum chromogranin A levels, performance status, or age." (PMID 41561737, 2025). "Chromogranin A (CgA) has been used as a valuable tumor marker in NETs, and elevated levels of both CgA and 5-hydroxyindoleacetic acid (5-HIAA) have previously been associated with poor prognosis in these patients." (PMID 40943444, 2025). "Immunohistochemically, this resected specimen revealed that the tumor was positive for synaptophysin, chromogranin A, CD56, and ACTH; the Ki-67-labeling index of the tumor cells was 2.7%." (PMID 41464537, 2025). "Compared with traditional biomarkers such as chromogranin A (CgA), ctDNA offers the distinct advantage of directly reflecting the tumor’s molecular landscape, potentially allowing earlier detection of disease progression." (PMID 40869136, 2025). "Univariate analysis did not reveal a statistically significant association between mDFS and age, gender, smoking history, tumor localization, TTF-1, chromogranin A, synaptophysin, CD56, adjuvant radiotherapy, or type of surgery." (PMID 41153253, 2025). "Both SYP and CHGA, markers of differentiated chromaffin cells, showed weaker staining in organoids compared to the primary tumor tissue." (PMID 40576438, 2025). "Immunohistochemistry showed tumor cell positivity for chromogranin A, synaptophysin, CD56, vimentin, GATA3, and S100, consistent with neuroendocrine origin, which supports the neuroendocrine diagnosis." (PMID 40964595, 2025).
tumor (continued). "Among the 9 patients with a SB NET (all in the detected cancer group), serum Chromogranin A and platelet serotonin tumour markers were elevated in 50% (n = 3/6) and 25% (n = 1/4) of cases with data available, respectively." (PMID 40974481, 2025). "Pathologically, 82% of tumours were classified as Grade II/III, with a high median tumour size (3.7 cm) and elevated serum Chromogranin A levels." (PMID 41726025, 2025). "Tumor progression was monitored using somatostatin receptor scintigraphy, chromogranin A, and contrast-enhanced CT." (PMID 40648806, 2025). "Immunohistochemical staining supported the diagnosis: tumor cells were positive for chromogranin A, synaptophysin, and S-100." (PMID 41467146, 2025). "In contrast, immunohistochemical staining of SCCOPT tumor tissues generally shows positive staining for chromogranin A, CD56, synaptophysin, and neural-specific enolase." (PMID 40071085, 2025). "In their study, the tumor grade was inversely proportional to the immunohistochemical expression for Chromogranin A and S-100." (PMID 39591360, 2024). "There were also significant elevations in tumor markers, with chromogranin A at 3000 ng/mL (normal: <100 ng/mL)." (PMID 39685871, 2024). "The tumor markers of NET were significantly raised with serum chromogranin A of 44,520 ng/dL and urinary 24-hour 5-hydroxyindole acetic acid (24-h 5-HIAA) of 32.40 mg/24 hours." (PMID 39677350, 2024). "According to Aresu, antibodies targeting Chromogranin A and S-100 are useful markers for this differentiation, as well as for assessing tumor grade and prognosis concerning histological criteria." (PMID 39591360, 2024). "Regarding the tumor marker analysis, chromogranin A levels were significantly elevated (3000 ng/mL), as stated." (PMID 39685871, 2024). "The pathways of ‘Protein folding’, ‘RNA splicing’, ‘Regulation of mRNA metabolic process’, ‘Regulation of mRNA processing’ and ‘Regulation of RNA splicing’ exhibited heightened enrichment in C4 CHGA+ tumour cells." (PMID 38894657, 2024). "The immunohistochemical results showed that the tumor cells were diffuse and positive for chromogranin A (CgA), synaptophysin (Syn), and INSM1." (PMID 39518315, 2024). "At immunohistochemistry (IHC), tumor cells are positive for keratin, neuroendocrine markers including synaptophysin and chromogranin-A, and glucagon." (PMID 39331358, 2024). "All neoplasms were investigated with immunohistochemistry for neuroendocrine markers (Synaptophysin, Chromogranin-A), ATRX, DAXX, ARX, and PDX1 transcription factors." (PMID 39331358, 2024). "All 12 primary tumours were immunohistochemically positive for chromogranin A, synaptophysin, and their respective secreted hormones." (PMID 39122816, 2024). "Meanwhile, immunocytochemistry staining showed robust expression of Chromogranin A (CGA) in these tumor tissues." (PMID 38407266, 2024). "Low-cost, easily available, but highly useful investigation like ESR and tumor markers (Chromogranin A, CA 19.9) need special emphasis in the treatment guidelines." (PMID 39430421, 2024). "Focal positivity for chromogranin A (CgA) and synaptophysin (Syn) was observed in the tumor cells of GCA." (PMID 38500658, 2024). "His tumor markers increased to 14,740 ng/dL for serum chromogranin A and 15.8 mg/24 h for urinary 5-HIAA, indicating progressive disease." (PMID 39677350, 2024). "The clinical tumor marker chromogranin A normalized after 2 weeks of lorlatinib treatment and has remained within the reference interval." (PMID 39177282, 2024). "Tumor markers exhibited a dramatic drop within 15 days after selpercatinib initiation; calcitonin levels normalized, and chromogranin A levels plummeted from 2900 to 190 ng/ml." (PMID 39085487, 2024). "Immunohistochemistry showed that the tumor cells diffusely and strongly expressed cytokeratin, synaptophysin, chromogranin A, GATA3, and CAM5.2." (PMID 38115331, 2023).